TNC (tenascin C)
Diseases named in the same sentence as TNC in open-access papers (continued):
Sharing a sentence is not in itself a finding about the gene and the disease.
tumor (continued). "Enzymatic depletion of HA from tumors, using the hyaluronidase PEGPH20, remodels the tumor microenvironment by decreasing at least collagen 1 and 5 and tenascin-C content and leads to tumor growth inhibition associated with a reduction in DNA synthesis." (PMID 24213471, 2012). "Two of these markers, CD44 and Tenascin C, which are expressed in the stem cell niches of normal brains, are expressed at much higher levels in the perivascular niche where tumor stem cells are proposed to reside." (PMID 22393407, 2012). "Since TNC overexpression correlates with poor tumor differentiation in vivo, we focused our study on the poorly differentiated cell lines PANC-1 and SU.86.86." (PMID 21747918, 2011). "Changes in the profile of TNC isoforms expressed in tumours compared with normal tissue have been described." (PMID 20678196, 2010). "The highly expressed tenascin-C in tumor stroma can stimulate tumor cell proliferation by stimulating signal transduction pathways." (PMID 20485485, 2010). "In keeping with this, changes in the pattern of TNC isoform expression have been described in a number of malignancies, the nature of which appears to be tumour-type specific." (PMID 19405959, 2009). "Many human tumor samples also gained expression of a coordinately regulated module associated with advanced malignancy (ABCC1, FOXO3A, LIF, PIK3R1, PRNP, TNC, TIMP3 and VEGF)." (PMID 17615082, 2007). "Tenascin-C expression occurs primarily around tumour-supplying blood vessels, with this staining pattern becoming more pronounced with increasing tumour grade." (PMID 15083170, 2004). "Tenascin-C is a hexabrachion polymorphic glycoprotein that is overexpressed in the extracellular matrix in high-grade gliomas as well as other tumour types." (PMID 15083170, 2004). "While the reviewed studies have primarily focused on tumor-associated antigens such as PD-L1, EGFR, Tenascin-C, ED-B, and CD44v6, recent advances in immunoPET have expanded the field toward imaging functional immune dynamics, particularly T-cell activation and exhaustion." (PMID 41211421, 2025). "TNC also contributes to tumor survival, proliferation, invasion and lung metastasis." (PMID 39754146, 2025). "It has been postulated that TNC is overexpressed at the mRNA and protein levels in tumor tissue from patients with NSCLC and that its degradation may also have biological significance." (PMID 40981103, 2025). "A related pattern was shown for tenascin C. On one hand, tumoral tenascin C drives tumor progression by polarizing macrophages into the M2 phenotype, while, on the other hand, host-derived tenascin C (presumably from stromal and/or immune cells) polarizes the macrophages into the M1 phenotype." (PMID 40592236, 2025). "Tenascin-C (TNC) is a secreted extracellular matrix protein that is highly expressed during embryonic development and re-expressed during wound healing, inflammation, and neoplasia." (PMID 39951495, 2025). "Notably, tenascin C was recently shown to facilitate tumour progression in a carcinogen-induced immunocompetent murine model of oral squamous cell carcinoma by promoting an immune-suppressive stroma." (PMID 41009413, 2025). "In addition to commonly found molecules such as collagens and fibronectin, the production of tenascin-C is also important and can be found in both the tumour stroma and the healing wound." (PMID 41009413, 2025). "TNC has been shown to be overexpressed at the mRNA and protein levels in tumor tissue from patients with NSCLC compared with adjacent normal tissue, and its expression is correlated with unfavorable clinical outcomes, larger tumor size, lymph node metastasis, and disease recurrence." (PMID 40981103, 2025). "Calcitriol exhibits anti-inflammatory effects on tumour cells through pathways such as suppression of prostaglandin action and effects related to tumour growth, invasion and angiogenesis through inhibiting the expression of tenascin-C." (PMID 38480934, 2024).
tumor (continued). "GD2 could interact with the extracellular matrix protein tenascin-C in cancerous tissues to disrupt cell adhesion and inhibit focal adhesion formation, thus elevating the metastatic potential of tumor cells." (PMID 39616302, 2024). "In this study, we identified TNC as a downstream regulator of tumor suppressor ZNF750." (PMID 38711034, 2024). "Furthermore, chi-square test revealed a significant correlation between ZNF 750 or TNC expression and tumor differentiation, clinical stages, and invasion depth." (PMID 38711034, 2024). "Importantly, the cancer cell and fibroblast co-transplantation tumor model confirmed that pGSN overexpression reduces TNC expression and attenuates CAF activation, thereby suppressing tumor growth." (PMID 39261905, 2024). "The interplay between FN and TNC in tumor angiogenesis is complex and puzzling." (PMID 38660622, 2024). "During their expansion from this region to other regions, such as clusters 6 and 3 regions, the tumor cells exhibited a more malignant expression pattern, such as high expression levels of malignant markers, such as TNC and TGFBI, as well as active proliferation markers, such as FOS and WEE1." (PMID 39639005, 2024). "Notably, we found a positive correlation between skin acanthosis severity and TNC expression, as well as between the expression of neuronal marker βIII tubulin and TNC." (PMID 37037861, 2023). "Therefore, our study revealed that low expression of FLNA, DPYSL3, KRT5, and TNC promotes tumor migration and development during the pathogenesis of PCa." (PMID 37251946, 2023). "The role of TNC in tumor progression and metastasis is well established." (PMID 37098922, 2023). "Upregulation of TNC can increase tumor cell metastasis to lymph nodes and bones in vivo." (PMID 37251946, 2023). "Among these, Tenascin-C (TNC) showed the highest consistent log2 fold-change, and verification by immunohistochemistry confirmed a marked increase in Tenascin-C protein levels in tumor compared to PTT." (PMID 36508875, 2023). "Moreover, TNC interacts with cell surface receptors, including integrins, to promote tumor cell adhesion and migration." (PMID 37759229, 2023). "Furthermore, the mRNA levels of FAP and TNC genes were significantly upregulated in PanCK(-) AOIs at the tumor invasive margin compared to the adjacent normal or tumor center." (PMID 37964075, 2023). "Furthermore, specific ECM proteins like elastin, laminin, tenascin-C, and periostin, when overexpressed, support tumor cell migration and survival." (PMID 37895855, 2023). "However, overexpression is frequently observed in cancer at the invasive tumor front, implicating tenascin-C in tumor progression and metastasis." (PMID 38067320, 2023). "However, A172 cells exhibit a higher level of the GSC marker CD133/2, mesenchymal markers CD90 and CD105, fibroblast activation protein, and tenascin C, which exert protumorigenic functions in the formation of tumor stroma." (PMID 36836827, 2023). "Although each have been described to be expressed in the ECM surrounding cancer cells, tenascin-C and tenascin-W are currently the most promising candidates for exploitability and clinical use as they are highly expressed in various tumor stroma with relatively low abundance in healthy tissues." (PMID 35785162, 2022). "As a vital component of the extracellular matrix (ECM) in the tumor mass, tenascin-C (TN-C) may have multifaceted and complicated roles in tumor progression." (PMID 35246056, 2022). "A current study by He-S and colleagues highlighted the fact that EWS-FLI1 induced tenascin-C (TNC) may regulate ES tumor progression through targeting the lncRNA MALAT1, and that this may be done by integrin α5β1-mdiated YAP activation." (PMID 35455947, 2022). "HOTAIR and the SNHG12–miR-330-5p–TNC axis might promote tumor progression via tumor cell metastasis and tumor hypoxia." (PMID 35968275, 2022).
tumor (continued). "Similar to antibodies, centyrin conjugates – small, engineered proteins derived from a human protein Tenascin C – have been designed to bind with high affinity and selectivity to numerous antigens, which makes specific tumour targeting across a broad range of tumour antigens feasible." (PMID 35188077, 2022). "In the 4T1-bearing mice from the 100 IU+cal group, increased NFs activation (increased α-smooth muscle actin, podoplanin, and tenascin C (TNC)) with a decreased blood flow in the tumor was observed, whereas the opposite effect was observed in the 5000 IU and 100 IU groups." (PMID 36230508, 2022). "TNC is also expressed in metastatic niches such as the bone, lungs, lymph nodes, and functions as a chemoattractant providing a suitable milieu for disseminated tumor cells to survive and form overt tumors." (PMID 35948987, 2022). "Therefore, TNC is considered to be a key molecule that promotes the formation of a tumor-supportive tissue microenvironment." (PMID 35444665, 2022). "As the TNC-KO mouse is viable, this mouse model has proven a useful tool to interrogate whether host- and tumor-derived TNC have similar or distinct functions." (PMID 36102918, 2022). "Similarly, TNC expression has also been found in developing cells, such as progenitors during development, tumor stroma and mesenchymal stem cells." (PMID 36522320, 2022). "Tenascin-C (TNC) may also serve as a tumor biomarker that promotes epithelial–mesenchymal transition, proliferation and the migration of cancer cells." (PMID 36005209, 2022). "Crossin showed that exogenously added TnC inhibited cell proliferation of fibroblasts in vitro even in the presence of mitogenic stimulators such as growth factors and tumor promoters, by inducing early inhibition of the intracellular alkalinization that occurs upon mitogenic stimulation." (PMID 36092707, 2022). "Therefore, the aim of this review is to summarize current knowledge on the tumor biological importance of Ln332 and its interaction with fibronectin (Fn) and tenascin-C (Tn-C) as relevant components of the ECM in the development and progression of OSCCs." (PMID 36230826, 2022). "Indeed, when we deleted host tenascin-C we found that, in contrast to deletion of tumor-derived tenascin-C, this resulted in diminished M1-like macrophage behavior." (PMID 33718177, 2021). "TNC is also upregulated in neoplastic lesions of salivary glands and mostly observed in a less differentiated and higher degree of malignancy tumours, such as solid adenoid cystic carcinomas, in oral leukoplakia, lichen planus, in oral submucous fibrosis and inflammatory gingival hyperplasia." (PMID 34205668, 2021). "Similarly, antibodies targeting tenascin C delayed tumor growth and induced apparent cures in murine xenograft models." (PMID 34200480, 2021). "Our a priori hypothesis was that tumour-free lymph nodes from pN+ patients would have more extensive tenascin-C expression than would nodes from pN0 patients." (PMID 34564696, 2021). "TnC emerges as a key regulator of multiple inflammatory processes, both during physiological tissue repair as well as pathological conditions ranging from tumor progression to cardiovascular disease." (PMID 33981316, 2021). "TNC is a key tendonogenic protein in the extracellular matrix glycoprotein family that often exhibits reduced expression in normal adult tissues but exhibits increased expression during embryonic development, tumor, injury repair, and inflammation." (PMID 35141140, 2021). "To determine whether tumour EVs upregulate tenascin-C in primary fibroblasts via the NF-κB pathway, we included an NF-κB inhibitor, dehydroxymethylepoxyquinomicin (DHMEQ), in combination with J82 EV treatment." (PMID 34564696, 2021). "As PSCs do not express the MET receptor, inhibition of the HGF/MET axis by the Combo treatment cannot directly influence the PSC status, but must be the consequence of a cross-talk between the tumor and the stroma compartment, which probably occurs through TNC." (PMID 34298732, 2021).
tumor (continued). "Exosomes have also recently emerged as efficient platforms for immunomodulation in the tumor microenvironment and other tissue contexts; it is likely that the prominent roles TnC has as a regulator of immune cell function (see first section) are exerted at least in part through exosomes." (PMID 33981316, 2021). "Besides, Tenascin C (TNC), ranking as the 2nd top upregulated gene in OLP, encoded an extracellular matrix protein (ECM) and was a promoter of tumor metastasis with multiple functions." (PMID 34615554, 2021). "The presence of tenascin-C in the reticular fibers of lymphoid organs and in tumor matrix tracks is remarkable and may represent an ancient defense program that is reused, or perhaps better characterized as mis-used, in cancer." (PMID 33912190, 2021). "Tenascin-C has already been targeted by a recombinant antibody–cytokine fusion protein for delivery of IL-2 into tumours, and it may be that a similar approach could be used to deliver compounds to the pre-metastatic niche." (PMID 34564696, 2021). "TNC is frequently expressed in embryonic tissue and in some adult tissue such as stem cell niches, but is mainly expressed de novo under pathophysiological conditions, especially during wound healing and tumor progression." (PMID 34944807, 2021). "However, the finding of the prognostic significance of tenascin-C expression in the tumour-free lymph nodes of the entire study group is further evidence of pre-metastatic niche formation in MIBC." (PMID 34564696, 2021). "High expression of tenascin C in si-hVDAC1-2A-TTs occurred in the zone of tumor–stroma interaction." (PMID 34200480, 2021). "It would be interesting to determine whether tumour or stromal EVs deliver tenascin-C from the tumour region to pre-metastatic sites and thus contribute to extracellular matrix remodelling or other aspects of pre-metastatic niche conditioning." (PMID 34564696, 2021). "We hypothesised that the cytokine levels found in patient urinary EVs would correlate with tenascin-C expression in tumour-free patient lymph nodes." (PMID 34564696, 2021). "While TNC is highly expressed in neurons during development, the protein is indicative of growth and repair processes in adult tissue at sites of trauma, inflammation, and tumor development." (PMID 33585555, 2020). "It is possible that tenascin-W plays a role similar to tenascin-C in the creation of an immune-suppressive environment in tumor stroma, though this hypothesis needs to be tested." (PMID 33603752, 2020). "Then, we further studied TNC expression at the protein level in TNBC primary tumours." (PMID 32732922, 2020). "Studies with normal human tissue samples suggest that the expression of tenascin-W may be more restricted in the adult than tenascin-C and may therefore be a better marker of tumor stroma and a more appropriate target for biotherapies." (PMID 33692777, 2020). "Another ECM protein, Tenascin C is up-regulated following injury and during tumor progression." (PMID 31952223, 2020). "We clarified whether TAMRA-FP hotspots localize to tumor regions undergoing matrix remodeling using the stiffness markers pMLC2 and tenascin C along with HA and CD44." (PMID 32190011, 2020). "Recently, Yang and colleagues demonstrated that tenascin-C displays potential in amplifying cancer stem-like properties, at least in part, indicating that tenascin-C may be involved with tumor recurrence." (PMID 32079295, 2020). "Until routinely applied anticancer drug combinations are available simultaneously targeting HGF, EGF and NFE2L2 mediated pathways, inhibition of overexpressed DYNLL, TNC, NCL and TMED2 may exert anti-tumor effect on HNSCC beyond their diagnostic role." (PMID 32564264, 2020). "In addition, high TNC expression was significantly associated with poor RFS in patients with basal tumours, but the opposite trend was observed in patients with luminal A tumours." (PMID 32732922, 2020).
tumor (continued). "Tenascin-C may also play a role in creating an immune suppressive tumor stroma, thus contributing to tumor growth and metastasis." (PMID 33692777, 2020). "Since tenascin-W seems to a be a more specific tumor marker than tenascin-C, tenascin-W might represent an additional tumor antigen that could be used as target for antibody-based therapies." (PMID 31032255, 2019). "Tumor exhibited a high-level expression of tenascin-C, which was found to colocalize with CAF." (PMID 30871158, 2019). "As with tumor-associated FN, TNC is not usually expressed in normal cells except in immune tissues, such as bone marrow and thymus gland, but is specifically expressed in malignancy, inflammation and wound healing." (PMID 31140150, 2019). "We found tumor specific TNC gene and protein overexpression that directly correlated with higher tumor grade (WHO III and IV, p = 0.05), H3K27 M mutation (p = 0.012), shorter progression free survival (p = 0.034), and poorer overall survival (0.041) in association with these factors." (PMID 31092287, 2019). "In particular, the F16 monoclonal human antibody specifically recognizing the alternatively spliced A1 domain of tenascin-C is being evaluated in clinical trials in combination with approved anti-tumor drugs in patients with solid tumors and metastatic breast cancer." (PMID 31032255, 2019). "We envision that TNC might be regulated downstream by one or more than one of these oncogenic drivers that in turn regulates the tumor cell growth differentiation." (PMID 31798767, 2019). "KEGG pathway enrichment analysis revealed that the mechanism by which TNC regulates ES tumour progression might be correlated with Hippo signalling pathway." (PMID 31649319, 2019). "Furthermore, the knockout of TNC inhibited ES cell proliferation, migration, and angiogenesis in vitro, which indicates that TNC promotes ES tumour progression in an autocrine manner." (PMID 31649319, 2019). "Tumor cell proliferation, invasiveness, and migration are critical for VM formation;33 concurrently, cell growth, invasion, and migration were inhibited upon TNC knockdown." (PMID 31754182, 2019). "Moreover, since CD99 is a specific marker for ES found in the cytoplasmic membrane of 100% ES tumour cells, the IHC double-staining method was applied to detect the co-expression of TNC and CD99 in ES tissue." (PMID 31649319, 2019). "TNC is a secreted protein, and has major functions in tumor initiation, progression and metastasis." (PMID 31798767, 2019). "Later, the tumor stroma becomes the source for tenascin C which maintains the metastatic growth." (PMID 31330946, 2019). "In agreement with our results, tenascin-C expression has usually been observed in the tumor stroma." (PMID 28978001, 2017). "Previous studies have suggested that tenascin-C could be used as a biomarker of tumor invasion and metastasis and as a prognostic factor in various cancers." (PMID 28978001, 2017). "Furthermore, Tenascin-C expressing neuroblastoma cells can transdifferentiate into tumor cell-derived ECs." (PMID 29112161, 2017). "They used GBI-10 to screen tumor markers and obtained tenascin-C." (PMID 29872716, 2017). "Therefore, we indicated that TNC regulated tumour cell motility by regulating focal adhesion function via activation of multiple signalling pathways, namely JNK/Paxillin/FAK." (PMID 29088796, 2017). "In addition, two other targets frequently found expressed in GCT tumor tissues are the glycoprotein of the extracellular matrix tenascin C (TNC) and the Epidermal Growth Factor Receptor (EGFR), described associated with GCT tumor progression." (PMID 28968976, 2017). "In addition, in colon cancer, tenascin-W, in contrast to tenascin-C, is ectopically expressed in tumor tissue and is considered as cancer biomarker of unfavorable disease progression, since it is not detectable in healthy colon stroma." (PMID 29112161, 2017).